INS (insulin)
Diseases named in the same sentence as INS in open-access papers (continued):
Sharing a sentence is not in itself a finding about the gene and the disease.
type 2 diabetes (continued). "Despite the fact that insulin is the oldest available treatment, and still an important treatment option for type 2 diabetes, there are very few large-scale randomized trials comparing insulin with other treatments, which have an appropriate duration for an assessment of cancer risk." (PMID 23209929, 2012). "As expected, the combination of HF feeding and low doses of STZ resulted in marked hyperglycemia with the characteristics of overt type-2 diabetes, namely, failed compensatory increase in blood insulin levels with concurrent hypertriglyceridemia and fatty liver." (PMID 22860063, 2012). "The MAGIC investigators reported a number of loci that influence fasting glucose and fasting insulin levels in non-diabetic populations of European descent; only a few of the loci were also associated with type 2 diabetes at genome-wide levels of significance." (PMID 22984506, 2012). "First, the postprandial insulin response to the LoBAG30 diet is vigorous and insulin is reported to decrease whole body protein degradation and possibly stimulate protein synthesis, although this effect is blunted in men with type 2 diabetes." (PMID 22607113, 2012). "However, because of progressive insulin depletion, the majority of patients with type 2 diabetes will require insulin to achieve optimal glycaemic control 5–10 years after diagnosis." (PMID 22545648, 2012). "This variation’s impact on insulin sensitivity may be more important with regard to a role in the pathogenesis of type 2 diabetes since its effect on insulin release vanishes with increasing BMI." (PMID 23094072, 2012). "Furthermore, while some key findings resonate with those from studies involving type 2 diabetes patients, our study was restricted to type 1 diabetes patients, and, more specifically, to those converted to flexible intensive insulin therapy." (PMID 22891794, 2012). "Further, a recent study supports our results and hypothesis by showing that inhibition of sEH restored glucose homeostasis and insulin signalling together with increased pancreatic islet size in a mice model of type II diabetes." (PMID 22007192, 2012). "In addition to failure of β cells to secrete insulin, the α-cell dysfunction in type 2 diabetes seems to result from insulin resistance of these glucagon-producing cells." (PMID 22479612, 2012). "Consequently, blood glucose levels increase and more insulin is released producing hyperinsulinaemia, which is manifested early in type 2 diabetes." (PMID 22470480, 2012). "The insulin dose of Chinese type 2 diabetic patients in our study may be different from that reported in the Caucasians." (PMID 22720003, 2012). "We therefore undertook the present study to test whether the genetic variability of CACNA1E affects key metabolic phenotypes (beta cell function and insulin sensitivity, both assessed by state-of-art methods) in patients with newly diagnosed type 2 diabetes." (PMID 22427875, 2012). "Whereas type II diabetes is known as the insulin resistant form, insulin is produced however the target tissues become insensitive or resistant to the action of insulin thereby not utilizing blood glucose correctly and as a consequence increasing circulating blood glucose levels." (PMID 22462028, 2012). "Also significant beneficial effects of daily intake of soluble and insoluble fiber (25 g each) were observed for six weeks, in patients with type 2 diabetes under pharmacological treatment, which showed decrease in insulin levels." (PMID 23088514, 2012). "Type 2 diabetes (T2D) occurs when the pancreatic beta cells can no longer compensate for peripheral insulin resistance by increasing insulin production and is associated with hyperglycemia and an altered lipid profile (dyslipidemia)." (PMID 22454629, 2012). "Levels of inflammation in type 1 and type 2 diabetes are still unknown, but it has been found that plasma levels of IL-6 correlate with C-peptide levels and insulin sensitivity." (PMID 22547909, 2012).
type 2 diabetes (continued). "For example, insulin given to type 2 diabetes patients in Japan was thought to induce T1D." (PMID 22567309, 2012). "However, clinical studies indicate that insulin therapy produces favourable effects on plasma lipid concentrations in patients with type 2 diabetes." (PMID 22081557, 2012). "The DESMOND SMBG trial has been designed to provide additional evidence to inform the debate around the value of SMBG for people with Type 2 diabetes (T2DM) not using insulin or at risk of hypoglycaemia." (PMID 22416896, 2012). "Since insulin is a physiological suppressor of glucagon secretion, relative insufficient insulin production or declined insulin action in type 2 diabetes may reduce intra-islet insulin action on the suppression of glucagon secretion from the α-cells." (PMID 23316165, 2012). "In conclusion, the augmented expression of c-Jun in diabetic islets decreases MafA activity followed by reduced insulin biosynthesis and secretion, and thereby explains, at least in part, the molecular mechanism for β-cell glucose toxicity that is often observed in Type 2 diabetes." (PMID 23202973, 2012). "This may be explained by the complexity of the pathogenesis of type 2 diabetes and the overlap regarding insulin sensitivity and beta-cell function." (PMID 23251434, 2012). "Moreover, SFAD sows had a deficient insulin secretion, confirming the diet-induced β-cell dysfunction suggested by prior changes in HOMA-β and evidencing the prodrome of type 2 diabetes." (PMID 22629144, 2012). "Evidence for the destruction of pancreatic islet cells by IL-1 was first provided for type 1 diabetes, but in type 2 diabetes IL-1ß and other proinflammatory cytokines also disrupt insulin signaling, and IκB kinase ß links obesity-induced IR and inflammation through activation of NFκB." (PMID 23028961, 2012). "This study adds that the stricter adherence to therapeutic recommendations, including the use of insulin therapy, might serve to improve blood glucose control among patients with Type 2 diabetes." (PMID 21294772, 2011). "In contrast, in the present study it was intriguing to find that SNP rs1241321, which did not affect the plasma ADMA level, was associated with insulin sensitivity, the risk of type 2 diabetes and their long-term outcome." (PMID 21303562, 2011). "Although the hallmark of obesity associated type 2 diabetes (T2D) is the decrease in insulin sensitivity, the development of hyperglycemia requires the failure of the allostatic response of the β-cells to respond by producing enough insulin to overcome the functional defect in insulin action." (PMID 22208362, 2011). "We now report a sub-study of the parent study, where our current goal is to simultaneously measure the changes in plasma hsCRP, TNF-α and interleukin-6 after a mixed-meal breakfast in patients with Type 2 diabetes and relate these changes to those of post-meal glucose, insulin and triglycerides." (PMID 21517955, 2011). "However, in type 2 diabetes, insulin sensitivity is decreased in extrahepatic tissues, mainly skeletal muscle, leading to markedly impaired insulin activation of the insulin signaling cascade and GLUT4-translocation." (PMID 21818330, 2011). "It was reported that INCB013739 treatment of type 2 diabetes mellitus patients who failed on metformin monotherapy could significantly improve hepatic and peripheral insulin sensitivity and reduce haemoglobin A1c and fasting plasma glucose." (PMID 21608132, 2011). "Therefore, a 50/50 mix of prandial + basal insulin can approximate normal insulin secretion and we recently showed that it can be used to control both pre- and post-meal hyperglycaemia in patients with Type 2 diabetes." (PMID 21517955, 2011). "Interestingly, the insulin-sensitizing PPARγ agonists used for treating type 2 diabetes, such as rosiglitazone and pioglitazone, have proven useful at ameliorating IBD effects in humans with UC." (PMID 21904603, 2011).
type 2 diabetes (continued). "The most important finding of the present study is that in this group of type 2 diabetic patients, a twelve-week training program, which increased aerobic capacity and insulin sensitivity resulted in an improvement of systolic function, while cardiac lipid content remained unchanged." (PMID 21615922, 2011). "Thus, in both animal models and in Type 2 diabetes patients Imatinib seems to improve glycemic control, possibly via an insulin sensitizing effect." (PMID 21935477, 2011). "We further verified the results by comparing HOMA-derived insulin sensitivity and different metabolic variables in lean and obese individuals with or without a genetic predisposition for Type 2 diabetes or overweight/obesity." (PMID 21532749, 2011). "Several of these KEGG terms were related to obesity, adipocyte differentiation and metabolic dysregulation; including MAPK signaling pathway, Insulin signaling pathway, Type II diabetes mellitus and Adipocytokine signalling pathway, suggesting relevant functionality." (PMID 22102887, 2011). "Based on our data, it is unclear whether protein ingestion would augment the glucose-lowering effect of prior RE in Type II diabetics, in whom insulin secretion and glucose transport are impaired." (PMID 21701685, 2011). "Improving insulin sensitivity with the peroxisome proliferator-activated receptor (PPAR-)γ agonist pioglitazone was demonstrated to reduce the occurrence of macrovascular events in patients with type 2 diabetes." (PMID 22098712, 2011). "Bilberry extract was also shown to reduce blood glucose level and enhance insulin sensitivity in type 2 diabetic mice via activation of AMPK (AMP-activated protein kinase), an enzyme central in the regulation of fuel preference, in adipose tissue, muscle- and liver cells." (PMID 21600021, 2011). "In terms of the possible mechanism of TRB3 implication in insulin resistence and hence in PCOS, studies has found that TRB3 is located on 20p13-p12 of human chromosomal region that has been confirmed to be associated with human type 2 diabetes." (PMID 21492415, 2011). "Recently, the MAGIC study conducted a large-scale meta-analysis and provided convincing evidence that the GCKR rs780094 A allele was associated with lower fasting glucose and insulin levels, a lower HOMA-IR index, a higher triglyceride level, and a lower risk for type 2 diabetes." (PMID 21569451, 2011). "In addition to RE, dietary modifications that acutely raise endogenous insulin secretion, represent a clinically relevant strategy to improve blood glucose homeostasis in Type II diabetes." (PMID 21701685, 2011). "Patients diagnosed as type I and type II diabetes mellitus(insulin requiring stage)." (PMID 21310088, 2011). "In addition, mice with homozygous deletions of IDE show a marked decrease in insulin degradation, while IDE polymorphisms have been associated with type 2 diabetes in humans." (PMID 21731629, 2011). "Results of the present study are clinically relevant, since improving insulin sensitivity may improve cardiovascular outcome, as was already suggested in patients with type 2 diabetes." (PMID 22098712, 2011). "Furthermore, type 2 diabetic Goto-Kakizaki (GK) rats with impaired insulin secretion and action also show hyperphagia and increased expression of NPY in ARC." (PMID 22081645, 2011). "Recently, small-molecule compounds have been discovered that specifically bind to the IR and augment IR-dependent signal transduction cascade, thereby mimicking the action of insulin and could be useful in the treatment of type 2 diabetes." (PMID 20008903, 2011). "Genetic predisposition for Type 2 diabetes, but not for overweight/obesity, was associated with inappropriate expansion of the adipose cells, reduced insulin sensitivity and a more proatherogenic lipid profile in non-obese individuals." (PMID 21532749, 2011). "One of the hallmarks of type-2 diabetes is decreased sensitivity of cells to insulin." (PMID 22104600, 2011).
type 2 diabetes (continued). "Insulin is the major hormone that regulates glucose metabolism in the periphery and the brain, so it can be expected that diseases with glucose dysregulation, namely Type I and Type II diabetes, will also have consequences on brain function." (PMID 22654727, 2011). "In type 2 Diabetes (T2D) free fatty acids (FFAs) in plasma are increased and hepatic insulin resistance is “selective”, in the sense that the insulin-mediated decrease of glucose production is blunted while insulin's effect on stimulating lipogenesis is maintained." (PMID 22087313, 2011). "Proteins and amino acids may reduce the insulin response in some clinical conditions such as obesity and type II diabetes." (PMID 21668975, 2011). "In type 2 diabetes, the pancreas fails to produce enough insulin, and evidence suggests that loss of beta cells contributes to this impairment." (PMID 21774832, 2011). "Type-2 diabetes is mediated by defects in either insulin secretion or insulin action." (PMID 22104600, 2011). "The logistic regression analysis showed that fetuin-A were associated with elevated HOMA-IR and fasting serum insulin both among the participants with or without type 2 diabetes in the full adjusted analysis." (PMID 21556362, 2011). "In conclusion, we hypothesize that sildenafil can be potentially used to improve insulin action in type 2 diabetic patients leading to new therapeutic strategies for type 2 diabetes and other related cardiovascular disease." (PMID 21297971, 2011). "However, our patients had well-controlled glycated haemoglobin levels (average 7.4%) and insulin use in persons with type 2 diabetes was high (95%)." (PMID 21283820, 2011). "We conclude that the oligomannuronate-chromium (III) complex might provide the basis for an adjuvant therapy of type 2 diabetes by enhancing insulin sensitivity with a lower toxicity profile than that of metformin." (PMID 21935427, 2011). "In addition, the combination of serum TSH and tissue insulin sensitivity has important effects on serum lipid parameters in type 2 diabetes." (PMID 20668706, 2010). "Several studies have shown that the magnitude of nutrient-stimulated insulin secretion is diminished in subjects with type 2 diabetes, promoting investigation as to whether incretin secretion and/or incretin action is diminished in diabetic subjects." (PMID 20470376, 2010). "Low VO2max values are often, but not always, associated with insulin resistance in white European and American populations, and low cardiorespiratory fitness is an independent predictor of type 2 diabetes risk." (PMID 21152018, 2010). "In more than 1,800 patients studied over 16 to 26 weeks, pioglitazone monotherapy was associated with increases of +0.9 to +2.6 kg as doses were uptitrated from 15-45 mg and increases of +2.3 to +4.1 kg in combination with insulin across the same dosing range in patients with type 2 diabetes." (PMID 20804556, 2010). "Type 2 diabetes only develops in insulin resistant patients with a concomitant β-cell defect." (PMID 20814545, 2010). "ATP turnover rate was observed to increase only after 1 h, indicating that glycogen synthesis is not limited by ATP availability in healthy controls, with implications for hypotheses about the origins of defective insulin sensitivity in type 2 diabetes." (PMID 20623795, 2010). "Impaired release or action of GLP-1 increases excessive insulin secretion, and may play a role in the development and/or progression of type 2 diabetes in patients with MetS." (PMID 20470376, 2010). "Another oral insulin in development for treatment of type 1 and type 2 diabetes is ORMD-0801." (PMID 21059246, 2010). "While a 60 mg/kg i.p. dose of STZ induced type 2 diabetes in the rat and suppressed the insulin output by about 82% of the control value (p<0.001), a pretreatment with any of the test compounds was able to preserve the ability of pancreas to secrete insulin following a treatment with STZ." (PMID 20804590, 2010).
type 2 diabetes (continued). "Type II diabetes mellitus is commonly known as non-insulin dependent diabetes, and is characterized by hyperglycemia and deficiency of secretion or action of endogenous insulin and associated with a number of vascular and neuropathic complications." (PMID 20931083, 2010). "However some individuals lack the underlying genetic program to adequately adapt, in which case insulin responses to circulating glucose progressively deteriorate, resulting in the development of type 2 diabetes." (PMID 20231880, 2010). "The Expectations about Insulin Therapy (EAITQ) and the Experience with Insulin Therapy Questionnaires (EWITQ) were administered at baseline and end-point, respectively to insulin-naïve patients with type 2 diabetes in a randomised trial comparing treatment algorithms for inhaled insulin." (PMID 20370840, 2010). "One study on type 2 diabetes patients showed increased levels of insulin after 12 weeks of diet supplemented with catechin-rich (582.8 mg) green tea, and another study revealed correlation between high intake of tea polyphenols and improved insulin levels in type 2 diabetes patients." (PMID 20480025, 2010). "INS was sequenced in 116 maturity-onset diabetes of the young (MODYX) patients (n = 48 Danish and n = 68 Czech), 83 patients with gestational diabetes mellitus (GDM), 34 type 1 diabetic patients screened negative for glutamic acid decarboxylase (GAD), and 96 glucose tolerant individuals." (PMID 20226046, 2010). "The 2.4-D associated adverse effects of decreased HDL, increased triglycerides, insulin, C-peptide, and TSH, may be part of a causal path that eventually may lead to weight gain, acute myocardial infarction, type-2 diabetes, and possibly other diseases." (PMID 20187939, 2010). "The physiological role of GIP in insulin release and fat metabolism combined with the fact that there is a reduction in the incretin effect in type 2 diabetes makes GIP and its receptor suitable candidate genes for genetic association studies in type 2 diabetes." (PMID 20673334, 2010). "Insulin-naïve people with type 2 diabetes (n = 8009), ≥ 35 years old, HbA1c ≥ 6.5% and begun on NPH (n = 1463), detemir (n = 357), glargine (n = 2197) or premix (n = 3992), were identified from a UK database of primary care records (The Health Improvement Network)." (PMID 20946269, 2010). "A mutation classically associated with adult-onset diabetes, i.e., V(A3)L, does not impair insulin chain assembly, and mutations at B24 give rise to only relatively small (2- to 4-fold) decrements in insulin yield." (PMID 20948967, 2010). "The insulin sensitizing agent, rosiglitazone, is a PPARγ agonist used in the clinic to treat type II diabetes and recently has been reported to affect the phenotypic switch of macrophages from a pro to an anti-inflammatory profile as well as to affect macrophage infiltration into the EF pad." (PMID 20445733, 2010). "I am confident in my ability to initiate insulin therapy for my type 2 diabetes patients." (PMID 20097652, 2010). "These disparate results with fasudil treatment between our study in Type 1 diabetes and the previous work in Type 2 diabetes may relate to differences in target tissue (kidney versus vasculature) or insulin levels." (PMID 20368772, 2010). "The significance of this in the treatment of type II diabetes could mean that in certain cases, higher plasma insulin levels could alleviate increases in plasma glucose concentrations." (PMID 20804585, 2010). "Adiponectin improves insulin sensitivity and may have anti-atherogenic and anti-inflammatory properties, and low plasma adiponectin levels have been shown to predict type 2 diabetes and coronary heart disease in humans." (PMID 21691545, 2010). "Conceivably, lack of CgB could also slow down the rate at which proinsulin is converted to mature insulin, as is the case in islets of human type-2 diabetics." (PMID 20126668, 2010).